FABP4 (fatty acid binding protein 4)
Diseases named in the same sentence as FABP4 in open-access papers (continued):
Sharing a sentence is not in itself a finding about the gene and the disease.
tumor (continued). "Furthermore, FABP4 can modulate inflammatory pathways crucial to tumor survival and growth under stress conditions." (PMID 39823981, 2025). "In terms of FA oxidation and intake, FABP4 regulates the FA metabolism of OC cells by disrupting tumor-infiltrating dendritic cells, thereby interfering with the anti-tumor immune environment, which often leads to widespread metastasis and poor prognosis of OC." (PMID 41421797, 2025). "Notably, FABP4 can act as both a tumor suppressor and an oncogene in different tumors, and is associated with immunotherapy and ferroptosis." (PMID 40119647, 2025). "Moreover, increased expression of FABP4 has been reported in various types of cancer cells, including PCa, affecting tumor cell proliferation, angiogenesis, and metastasis." (PMID 41226657, 2025). "Studies have discovered that the upregulation of FABP4 in CRC tissues could stimulate tumor growth by activating the fatty acid oxidation pathway." (PMID 41034734, 2025). "Interestingly, in this study we found an association of increased FABP4 and CD36 mRNA expression with poor prognosis in CRC, further suggesting the tumor-promoting properties of lipid metabolism upregulation." (PMID 39147895, 2024). "At the same time, a link between FABP4 and tumor metastasis has been continuously reported." (PMID 39035744, 2024). "Moreover, to investigate the potential interactions between FABP4+C1q+ macrophages and other immune cells in tumor microenvirment (TME), IHC staining was performed for CD4+ T cells, CD8+ T cells, CD20+ B cells." (PMID 39353883, 2024). "In particular, the very pronounced increase of FABP4 at the RNA and protein levels in both tumor cells and tumor stroma is a strong indicator of the validity of the hypothesis that the prognostic effect of SARIFA is driven by metabolic reprogramming." (PMID 39085485, 2024). "Important molecules involved in the lipolysis, transport, and uptake of exogenous fatty acids include the fatty acid binding protein 4 (FABP4), the fatty acid tissue translocase CD36, and the angiopoietin-like protein 4 (ANGPTL4), which have all been recently implicated in tumor biology." (PMID 39456610, 2024). "Consistently, soluble FABP4 enhanced MCF-7 tumor cell migration compared to the PBS control." (PMID 39054536, 2024). "Notably, lean mice or humans exhibited relatively low levels of circulating FABP4, but tumor-bearing mice or humans exhibited elevated levels of circulating FABP4, suggesting that tumors mobilized adipose tissue lipolysis for their growth benefits." (PMID 39054536, 2024). "Interestingly, the tumor growth rate in V9-treated mice was similar to that in FABP4−/− mice, suggesting that V9 antibody treatment exhibits an equal effect to FABP4 knockout." (PMID 39054536, 2024). "Similar to FABP4, the complement system has been suggested to be a double-edged sword that plays a critical role in both the prevention and promotion of tumorigenesis and tumor development." (PMID 39353883, 2024). "Altogether, FABP4 expression in macrophages was essential for LA-induced pro-tumor effects." (PMID 39513934, 2024). "FABP-4 expression in adipocytes has been reported to play a key role in the progression and metastasis of ovarian cancer by facilitating fatty acid supply for rapid tumor growth." (PMID 37833736, 2023). "FABP4 can regulate tumor growth, migration and invasion by affecting metabolism." (PMID 37260987, 2023). "Additionally, FABP4 plays a significant role in tumor transformation, proliferation, metastasis, and drug resistance by enhancing lipid transport." (PMID 38060103, 2023). "In our study, we also observed an overexpression of FABP4 in NAFLD-HCC tumor tissue." (PMID 37950277, 2023). "BMS309403, a small molecule inhibitor of FABP4, could not only significantly reduce tumor burden in a syngeneic orthotopic model but also increase the sensitivity of cancer cells towards carboplatin." (PMID 37277821, 2023).
tumor (continued). "In general, FABP4 may be correlated to pathways such as tumor cell proliferation, apoptosis, metabolism, and inflammatory responses." (PMID 36532833, 2022). "In addition, the prognostic value and targeting strategies of FABP4 in diverse tumor types are also discussed in this review." (PMID 35899119, 2022). "More importantly, FABP4 is a crucial driver of malignancy not only by activating the oncogenic signaling pathways, but also rewiring the metabolic phenotypes of tumor cells to satisfy the increased energy demand for tumor development." (PMID 35899119, 2022). "Therefore, the LPL/FABP4/CPT1 axis would generate a tumor microenvironment providing fatty acids for building blocks and energy production (i.e., fatty acid oxidization), which is essential for the proliferation of tumor-initiating cells." (PMID 35052876, 2022). "Expression patterns and clinical significance of FABP4 in diverse tumor types." (PMID 35899119, 2022). "FABP4 is a mediator of lipid metabolism in adipocytes and can provide fatty acids to tumor cells." (PMID 36338624, 2022). "In multiple tumor types, FABP4 is critical for tumor proliferation, metastasis and drug resistance." (PMID 35899119, 2022). "FABP4 could enhance tumor transport for increased LD content, which coordinates with FA desaturation mediated by stearoyl-CoA desaturase-1 (SCD1), to protect tumor cells from oxidative stress-induced ferroptosis." (PMID 35899119, 2022). "Recently, the effects of FABP4 on tumor malignant behavior were also reported, and it may represent a novel biomarker for cancer therapeutic target." (PMID 36264920, 2022). "Importantly, FABP4 contributes to the tumor transformation, proliferation, metastasis and therapy resistance by enhancing lipid transport and activating diverse oncogenic signaling pathways." (PMID 35899119, 2022). "This FABP4 positive subset of TAMs directly promotes tumor growth." (PMID 36060264, 2022). "Collectively, intracellular FABP4 is essential for the function of tumor-promoting macrophages." (PMID 35899119, 2022). "Meanwhile, FABP4 may be involved in tumor invasion and metastasis, and adipose microenvironment regulation located in tumor-surrounding tissues plays a critical role in the regulation of the tumor microenvironment (TME)." (PMID 36532833, 2022). "Furthermore, 30 clinical CRC tissues (including tumor tissues and the corresponding adjacent tumor tissues as well as normal tissues) were collected, and the expression of FABP4, HOXC9, INHBB, NKAIN4, and PLXNB3 was determined using RT-PCR." (PMID 35721480, 2022). "Indeed, FABP4 inhibition in a mouse model of PCa reduced tumor growth and metastasis, partly by inducing prostatic epithelial cell DNA damage and apoptosis." (PMID 35406450, 2022). "Thus, the small-molecule inhibitor (BMS309403) of FABP4 not only significantly reduced tumor load in syngeneic in situ mouse models but also increased cancer cell sensitivity to carboplatin both in vitro and in vivo." (PMID 35646090, 2022). "More importantly, FABP4 is a crucial driver of malignancy not only by activating the oncogenic signaling pathways, but also rewiring the metabolic phenotypes of tumor cells to satisfy their enhanced energy demand for tumor development." (PMID 35899119, 2022). "Overall, there is a crosstalk between cancer cells and the periprostatic adipose tissue, locally-produced adipokines support the development of the tumor microenvironment, and fatty acid-binding protein 4 (FABP4) released by adipocytes would constitute an energy source for tumor cell invasion." (PMID 36017326, 2022). "This FABP4 positive subset of TAMs directly promote tumor growth." (PMID 36060264, 2022). "FABP4 primarily functions as a promoter for tumor proliferation, metastasis and drug resistance." (PMID 35899119, 2022).
tumor (continued). "Interestingly, clinicopathological analysis demonstrated that a decrease in FABP4 expression was correlated with aggressive clinical and pathological characteristics, including increased tumour size, decreased differentiation status and advanced TNM stage." (PMID 35198079, 2022). "Moreover, FABP4 functions as a link between tumor cells and the components of TME, including adipocytes, macrophages and endothelial cells." (PMID 35899119, 2022). "FABP4 reprograms metabolic phenotypes to facilitate tumor growth." (PMID 35899119, 2022). "Elevated levels of circulating FABP4 in obese patients increase tumor stemness and aggressiveness." (PMID 35899119, 2022). "FABP4 has an important role in tumor proliferation, metastasis, and drug resistance, not only activating oncogenic signaling pathways but also remodeling the metabolism of tumor cells, providing energy requirements, and promoting tumor development." (PMID 36532833, 2022). "FABP4 activates a series of oncogenic signaling pathways to enhance tumor proliferation." (PMID 35899119, 2022). "It has been recently reported that FABP4 is closely related to the development of cancer and may be involved in tumor invasion and metastasis." (PMID 36532833, 2022). "FABP4 overexpression inhibits tumor growth through the activation of PPARγ." (PMID 36532833, 2022). "Fatty acid-binding protein 4 (FABP4) was found to facilitate the transfer of adipocyte-derived FAs between cancer-associated adipocytes and cancer cells, while CD36 facilitates FA uptake, thus providing tumours with sufficient energy to grow and progress." (PMID 35328822, 2022). "In addition, SCD1 and FABP4 are also thought to inhibit ferroptosis in tumor cells by inducing desaturation of fatty acids which is essential for tumor relapse in response to tyrosine kinase inhibitors (TKI) and chemotherapy." (PMID 36387147, 2022). "Knockdown of FABP4 regulates the differentiation of macrophages and inhibit tumor, suggesting that FABP4 could enhance tumor progression through macrophage differentiation." (PMID 36060264, 2022). "FABP4 has been shown to promote tumour progression via enhancement of new blood vessel formation and tumour growth mediated by its effects on adipocytes and tumour cells." (PMID 34572888, 2021). "Interestingly, clustered regularly interspaced short palindromic repeat (CRISPR)-mediated knockout of FABP4 in high-grade serous ovarian cancer cells reduced metastatic tumor burden in mice." (PMID 33498240, 2021). "Furthermore, unregulated expression of FABP4 has been recognized as critical indicators of tumor initiation and progression." (PMID 33407508, 2021). "Various studies showed that FABP4 inhibitors could restrict the progression of several tumours by inhibiting or reducing tumour cell proliferation, metastasis, and drug resistance." (PMID 34702269, 2021). "Moreover, adipose/macrophage FABP (A-FABP, FABP4) mediates ROS-mediated pro-tumor macrophage death induced by n–3 PUFAs." (PMID 34203461, 2021). "Moreover, FABP4 overexpression accelerated in vivo NB tumor growth, as indicated by the upregulation of Ki67." (PMID 33931964, 2021). "Interestingly, in the clinical datasets explored, FABP4 was the most common protein correlating with increased CD36 expression in 15 out of the 16 tumour types assessed." (PMID 34561446, 2021). "Moreover, IL1α depletion in CMs of macrophages enhanced proliferation and migration of SK‐N‐SH cells and blunted the tumor‐inhibiting effects of FABP4‐knockdown macrophages." (PMID 33931964, 2021). "The activation of fatty acid metabolism regulated by the LPL/FABP4/CPT1 axis may provide a tumor microenvironment conducive to the production of LCSCs, although the detailed mechanism remains to be further explored." (PMID 34803493, 2021). "The role of NF‐κB on tumor‐inhibiting effects of FABP4‐altered macrophages was also investigated." (PMID 33931964, 2021). "CD36 and FABP4 inhibition induces apoptosis in tumour cells." (PMID 34561446, 2021).
tumor (continued). "To determine whether macrophages‐derived FABP4 represents a general mechanism for promoting tumor progression, we further evaluated tumor growth and metastasis in vivo by using cell line‐derived orthotopic and metastatic NB models, respectively." (PMID 33931964, 2021). "FABP4, also known as aFABP and aP2, is a low-molecular-weight protein that transports LCFAs and other hydrophobic ligands, which takes an active part in the interaction between tumor and adipose tissue." (PMID 33407508, 2021). "In some in vitro systems FABP4 has been shown to promote EMT via TGFβ.Other CAA derived chemokines have been shown to support tumor progression by inducing a partial EMT in breast cancer models and can cooperate with endotrophin, a cleavage product of collagen VI α3 chain to promote EMT." (PMID 33590419, 2021). "FABP4‐mediated macrophages increased migration, invasion, and tumor growth of NB cells." (PMID 33931964, 2021). "Lipids arising from adipocytes have been demonstrated to increase tumor growth and invasiveness by increasing the expression of fatty acid binding protein 4 (FABP4), a fatty acid chaperone that is involved in glucose and lipid metabolism, heme oxygenase 1 (HMOX), and IL-1β in metastatic tumor cells." (PMID 32092997, 2020). "In PCa, both tumor cell-derived and peri-tumoral adipocyte-derived FABP4 may play a role in promoting tumor progression." (PMID 33352874, 2020). "Furthermore, enhanced expression of FABP4 was observed in WD and ob/ob mice relative to controls, with intense staining present in adipocytes and in tumor cells immediately adjacent to adipocytes." (PMID 33233362, 2020). "In addition, FABP4 can also play a role in carcinogenesis, as suggested by data that demonstrate a correlation between levels of the chaperone and tumor progression." (PMID 32856199, 2020). "There was a significant correlation between FABP4 expression and tumor grade." (PMID 32685482, 2020). "FABP4 is secreted from both PCa cells and adipocytes surrounding PCa tumors, and is believed to either shuttle fatty acids between adipocytes and tumor cells or act as an inducer of MMPs from cancer cells and cytokines (e.g., IL‐6, IL‐8) from stroma cells to promote invasion and metastasis." (PMID 33031638, 2020). "Therefore, the significantly enhanced metabolism induced by adipocytes was inhibited by FABP4 inhibitor, suggesting that FABP4 promoted tumor metabolism." (PMID 33088219, 2020). "In addition, FABP4 has been reported as predictor of residual disease in HGSC and its overexpression in patients’ tumours is associated with increased metastatic burden and poor survival." (PMID 30765860, 2019). "In addition, studies have reported that FABP4 affects cell growth and promotes tumor cell metastasis by carrying fatty acid transport energy or through the MAPK pathway." (PMID 31651326, 2019). "We performed gene expression to identify the molecular pathways that are potentially deregulated in HepG2 and HuH7 cells during eFABP4 stimulation to determine whether FABP4 affects tumor cells." (PMID 30575815, 2019). "Tumor-induced secretion may only be one of the reasons for the increase of FABP4 and FABP6 in peripheral serum." (PMID 31651326, 2019). "We confirmed the endothelial FABP4 tumor expression in an experimental HFD mice xenografted model." (PMID 30575815, 2019). "We showed the role of microvesicles as FABP4 vectors between endothelial and tumor cells." (PMID 30575815, 2019). "Curative treatment with BMS309403 significantly decreased tumor FABP4 (p = 0.04), cyclin D1 (p = 0.02), VEGFA (p = 0.002) and VEGFR (p = 0.001) expression compared to the control group, while active caspase 3 was induced (p = 0.008) in parallel with mTOR pathway downregulation." (PMID 30575815, 2019). "Knockdown of FABP4 may increase the expression levels of Snail and P‐Stat3 that were relevant with tumor progression and metastasis." (PMID 29733540, 2018).
tumor (continued). "In vivo, overexpression of FABP4 led to slowing tumor growth and decreasing tumor weight." (PMID 29733540, 2018). "The further study is needed to explore the tumor‐specific function of FABP4." (PMID 29733540, 2018). "Therefore, it is of high significance for treatment of inflammation, metabolic diseases, and inhibiting of tumor growth to develop new dual inhibitors with good pharmacokinetics and biochemical characteristics to target FABP4 and FABP5." (PMID 30142969, 2018). "FABP4 siRNA or a miR-409-3p mimic led to significant inhibition of tumor metastasis." (PMID 30050129, 2018). "In vivo, we confirmed that FABP4 suppressed tumor development in YY‐8103 cells." (PMID 29733540, 2018). "A pharmacological strategy using intravesical instillations of PPAR agonists could be applied to induce FABP4 expression in order to prevent tumour progression." (PMID 30526555, 2018). "In addition, the expression of PTEN, a major PCa tumor suppressor that interacts with FABP4, was inversely correlated with FABP4 expression." (PMID 29340091, 2017). "To determine whether increased serum levels of FABP4 and IL-8 modified tumor cell proliferation and invasive capacity, we performed ex vivo proliferation and invasion assays using serum harvested from mice." (PMID 29340091, 2017). "Interestingly, phosphatase and tensin homolog deleted on chromosome 10 (PTEN), a significant tumor suppressor of various cancers including PCa, interacts with FABP4, and FABP4 expression was higher in Pten-null keratinocytes compared with normal cells." (PMID 29340091, 2017). "However, vascular FABP4 expression in low-grade carcinomas was more than two-fold higher than FABP4 in the vessels of high-grade tumours." (PMID 27568980, 2017). "We observed that in the primary tumour, FABP4 expression in vessels within the stroma was significantly higher than in vessels directly adjacent to tumour cells and vessels in the tumour–stroma interface." (PMID 27568980, 2017). "Interestingly, in addition to the effects on PDK1, Atglistatin treatment increased the expression of lipid transporter fatty acid binding protein 4 (FABP4) in tumor cells grown in transwell with adipocytes." (PMID 27588494, 2016). "Our finding of the positive correlation between FABP3 and FABP4 expression suggest that these two proteins may act in the same signaling pathway in promoting tumor progression." (PMID 27323829, 2016). "As such, [125I]TAP1 could have applications for clarifying the relationship between tumor malignancy and the function of FABP4 in such tumors." (PMID 24732569, 2014). "As a mediator of lipid trafficking between adipocytes and tumor cells, FABP4 itself may be a viable candidate for therapeutic targeting." (PMID 24240026, 2013). "We also provide evidence of high FABP4 presence in experimental and patient prostate bone metastasis tissues and reveal the FABP4-PPARγ interaction as a potential driving mechanism of metastatic tumor growth in bone." (PMID 24240026, 2013). "Notably, these cells maintained high expression of FABP4 and IL-1β, further strengthening the link between FABP4/IL-1β axis and tumor invasiveness." (PMID 24240026, 2013). "Data presented in this study suggest that co-dependent interaction of this receptor with FABP4 may be a potential mechanism of tumor adaptation to the bone metastatic niche." (PMID 24240026, 2013). "In addition to its expression in adipocytes and tumor cells, FABP4 localizes strongly to endothelial cells and bone marrow cells, important components of bone metastatic niche." (PMID 24240026, 2013). "Notably, the closer the tumor cells were to adipose tissue, the stronger the FABP4 staining in these cells, suggesting that the ectopic FABP4 staining in these invasive frontline tumor cells may originate from adipose tissue." (PMID 40106183, 2025).